SOX9 (SRY-box transcription factor 9)
Diseases named in the same sentence as SOX9 in open-access papers (continued):
Sharing a sentence is not in itself a finding about the gene and the disease.
breast carcinoma (continued). "On the other hand, lots of TFs, like EN1, STAT3, SOX9, and FOXM1, showed essential oncogenic functions in non-luminal breast cancer." (PMID 34249704, 2021). "In contrast, HS578T-Hyg human breast cancer cells were positive for SLUG and CK14 and negative for SOX9 and CK8 expression." (PMID 28768501, 2017). "Indeed, Slug is able to collaborate with Sox9 to induce differentiated luminal mammary epithelial cells to enter the mammary stem cells without inducing EMT, and increase the tumorigenicity of nonmetastatic breast cancer cells." (PMID 36276640, 2022). "Moreover, we observed significant upregulation of several crucial stem cell factors such as Myc, Sox9 and BMI1 in response to elevated expression of KLF4 but not KLF4-3K, which suggests a critical role of KLF4 in the maintenance of self-renewal for breast cancer stem cell." (PMID 26420673, 2015). "Interestingly, comparative analysis of the basal‐like vs. luminal breast cancer cell types markers in ABI1 KO mice showed that the genes of basal‐like cells (Krt14, Vim) are responded to Abi1 depletion, however luminal cell type genes markers (Krt8, Krt18, Sox9, Estr1) do not." (PMID 34967509, 2022).
campomelic dysplasia (122 papers, 2007 to 2026). "A point mutation at position 76 (alanine to glutamic acid, A76E) of Sox9 is recognized as one of the causes of campomelic dysplasia." (PMID 42193997, 2026). "Campomelic Dysplasia (CD) is a complicated developmental disease caused by a loss-of-function allele in SOX9." (PMID 40025280, 2025). "Campomelic dysplasia, caused by SOX9 mutations, involves skeletal and genital anomalies, but is uniquely associated with bowed long bones and more severe respiratory complications." (PMID 40843254, 2025). "Campomelic dysplasia (CD), a severe developmental disorder characterized by systematic skeletal dysgenesis, has long been associated with SOX9 HI." (PMID 40025280, 2025). "For example, mutations in the SOX9 gene lead to Campomelic dysplasia, a severe skeletal malformation syndrome, while mutations in SOX10 are associated with Waardenburg–Hirschsprung syndrome." (PMID 39936824, 2025). "One such example is the SOX9 gene: breakpoints located more than 130 kb from the gene cause campomelic dysplasia in human patients." (PMID 40721267, 2025). "The transcription factor SOX9 is integral to tissue homeostasis and is implicated in skeletal malformation, campomelic dysplasia, and osteoarthritis (OA)." (PMID 39344191, 2024). "The T variant of rs2229989 in SOX9, the causative gene of Campomelic Dysplasia, was also found to be more prevalent in our FASD cohort when compared to controls." (PMID 38785976, 2024). "Mutations in and around SOX9 cause campomelic dysplasia (CD) characterized by skeletal malformations." (PMID 38855864, 2024). "Haploinsufficiency or heterozygous mutations within and around the SOX9 genetic locus causes skeletal malformation syndrome, and campomelic dysplasia (CD)." (PMID 39344191, 2024). "The reciprocal translocation in the breakpoint position located 203 kb upstream of the SOX9 gene was found to be associated with acampomelic campomelic dysplasia." (PMID 38245767, 2024). "To illustrate this approach, we examined the chondrogenic enhancer landscape at the SOX9 locus where deleterious mutations in the SOX9 gene itself have been shown to cause campomelic dysplasia (CD), a severe bone malformation." (PMID 38844479, 2024). "For example, mutations, deletions, inversions in SOX9, as well as in its upstream promoter and enhancer regions cause campomelic dysplasia, a condition associating skeletal malformations and to sex reversal in XY individuals." (PMID 38520033, 2024). "In humans, campomelic dysplasia caused by SOX9 haploinsufficiency is associated with chondrocyte hypertrophy and increased RUNX2 levels." (PMID 38885336, 2024). "SOX9 variants also result in sex reversal, with a well-established role in Campomelic Dysplasia, a severe skeletal dysplasia." (PMID 36672963, 2023). "Heterozygous mutations of SOX9 have been described in patients with campomelic dysplasia, a skeletal dysplasia characterized by bowed long bones and defects in cartilage formation." (PMID 38322155, 2023). "In humans, mutations of Sox9 are associated with inherited genetic birth defects, including campomelic dysplasia (CD), an autosomal dominant disease characterized by skeleton malformation, XY sex reversal, and a high neonatal lethality rate." (PMID 37681879, 2023). "Sox9 mutations in mice cause limb defects with abnormal skeletal muscle formation, whereas SOX9 mutations in humans cause severe skeletal dysmorphology, campomelic dysplasia." (PMID 37366057, 2023). "As noted, the SOX9 N-terminal region for dimerization was conserved and had multiple Campomelic Dysplasia-linked variants within the motif (I73T, A76E, L81V, and G83R)." (PMID 36672963, 2023). "All children had established syndromes (eg, X-linked lissencephaly/ATRX, campomelic dysplasia/SOX9, Scimitar syndrome), chromosomal deletions or complex multisystem involvement, often associated with fetal growth restriction." (PMID 36419940, 2022).
campomelic dysplasia (continued). "A striking example of incomplete penetrance comes from an individual that is healthy despite carrying a disease-causing mutation in SOX9, which usually causes campomelic dysplasia and leads to early childhood death." (PMID 35089335, 2022). "In humans, pathogenic variants of Sox9 can cause campomelic dysplasia (CD), a very serious condition that often results in death of patients in the neonatal period." (PMID 36354775, 2022). "Heterozygous variants in SOX9 cause campomelic dysplasia (OMIM: 114290) that can include HI as one of its clinical expressions." (PMID 35440622, 2022). "Heterozygous mutations in human SOX9 lead to Campomelic dysplasia (CMPD), with associated partial or complete XY sex reversal in around 75% of cases." (PMID 36114905, 2022). "Human SOX9 gene mutations contribute to campomelic dysplasia, a severe skeletal malformation syndrome with gonadal dysgenesis, indicating that SOX9 is a pivotal factor in controlling bone and testes development." (PMID 36522405, 2022). "Sox9 regulates chondrogenesis, and heterozygous mutations at the SOX9 locus cause the autosomal dominant disease campomelic dysplasia of humans." (PMID 35409417, 2022). "Mutations in the human SOX9 gene led to campomelic dysplasia, a haploinsufficiency disorder with several skeletal malformations frequently accompanied by 46, XY sex reversal." (PMID 36114905, 2022). "Heterozygous mutations in SOX9 lead to the human disorder campomelic dysplasia (CMPD, OMIM# 114, 290) characterized by skeletal dysplasia and variable 46, XY sex reversal." (PMID 36114905, 2022). "Deficiency of SOX9 leads to Campomelic dysplasia, characterized by facial and skeletal anomalies, including cleft palate, midface hypoplasia, short stature and short and bowed limbs." (PMID 33577554, 2021). "Mutations in human SOX9 result in skeletal abnormality, sex reversal syndrome, campomelic dysplasia (CD), which has a high lethality rate." (PMID 34639189, 2021). "In mice loss of function of one Sox9 allele results in smaller cartilaginous elements; similarly SOX9 haploinsufficiency in humans results in campomelic dysplasia (bowing of the limbs) affecting all endochondral bones." (PMID 33314394, 2021). "Mutations in the transcription factor gene SRY (sex-determining region Y)-box 9 (SOX9) cause campomelic dysplasia, and extensive functional analysis of SOX9 has defined it as a master regulator of the chondrocyte lineage." (PMID 34331943, 2021). "Mutations in SOX9 were originally identified as the cause for campomelic dysplasia, a severe skeletal dysplasia associated with XY sex reversal and disproportionally short stature, as well as general lack of cartilaginous tissue formation." (PMID 34235151, 2021). "Heterozygous loss-of-function mutations in the SOX9 coding sequence cause a severe congenital disorder called campomelic dysplasia, which is associated with bowed long limbs, disorders of sex determination, and craniofacial defects." (PMID 32991838, 2020). "Translocationsinvolving this region cause a clinical condition known as campomelic dysplasia bypresumptively altering SOX9 expression associated with skeletal defects." (PMID 30264949, 2019). "Sox9 was discovered by human genetic studies: Mutations in human SOX9 were associated with campomelic dysplasia (CD), which is characterized by skeletal malformation and XY sex reversal." (PMID 31847446, 2019). "The mutations in human SOX9 gene leads to campomelic dysplasia with skeletal malformation and dwarfism." (PMID 30140415, 2018). "Mutations in Sox9 cause campomelic dysplasia, a human skeletal dysmorphology syndrome often associated with male to female sex reversal." (PMID 30065900, 2018). "Mutations in SOX9 are known to cause Campomelic Dysplasia (OMIM #114290), characterized by a high forehead and a wide anterior fontanel, among other craniofacial characteristics." (PMID 29698431, 2018).
campomelic dysplasia (continued). "SOX9 mutations in humans produce campomelic dysplasia, a generally lethal osteochondrodysplasia with distinctive abnormalities in cartilage and bone." (PMID 29262782, 2017). "Disruption of upstream distal intergenic regions especially the regions between -50 kb and -350 kb 5′ of SOX9 by deletion/translocation/inversion are associated with severe campomelic dysplasia." (PMID 29262782, 2017). "For example, coding mutations in SOX9 are established causes of the lethal disorder campomelic dysplasia." (PMID 28754144, 2017). "Experimental loss of SOX9 abrogates limb development in mice and mutations in the SOX9 coding sequence lead to the skeletal malformation syndrome campomelic dysplasia (CD)." (PMID 29084806, 2017). "Campomelic dysplasia (CD) is a semilethal developmental disorder caused by mutations in and around SOX9." (PMID 28546996, 2017). "Comparison of phenotypic abnormalities in Stat3 loss-of-function mice relative to Sox9 haploinsufficient mice and patients with campomelic dysplasia." (PMID 28166224, 2017). "The molecular mechanism of campomelic dysplasia/autosomal sex reversal caused by SOX9 gene mutation shows that two heterozygous mutations, F154L and A158T, destroy the alpha helix of the HMG domain of SOX9." (PMID 28090537, 2016). "Most mutations in campomelic dysplasia result in haploinsufficiency for SOX9 and the phenotypic consequences include micrognathia and abnormal ears, as well as distinct skeletal abnormalities." (PMID 27622494, 2016). "Heterozygosity for mutations in SOX9 produces campomelic dysplasia, a generally lethal skeletal dysplasia." (PMID 27622494, 2016). "The upstream sequence mutation of the SOX9 gene causes abnormal cartilage formation (campomelic dysplasia, CD)." (PMID 28090537, 2016). "This network includes SOX9, a well-known regulator of cartilage differentiation, mutations of which lead in humans to Campomelic Dysplasia (OMIM #114290) a disorder characterized by a range of craniofacial defects." (PMID 27193062, 2016). "The deregulation of SOX9 is determining the final phenotypic outcome: translocation breakpoints close to SOX9 typically result in campomelic dysplasia, whereas those further upstream cause acampomelic campomelic dysplasia." (PMID 25606056, 2014). "Heterozygous mutations in Sox9 cause campomelic dysplasia, a generalized and severe disease of cartilage characterized by hypoplasia of endochondral bone." (PMID 25229425, 2014). "Human Sox9 heterozygous mutations cause Campomelic Dysplasia (CD), a condition characterized by several skeletal dysmorphologies including cleft palate and hypoplasia/bending of many endochondral bones." (PMID 25340762, 2014). "Heterozygous mutations in the Sox9 gene result in campomelic dysplasia, while haploinsuffuciency of SOX9 leads to chondrodysplasia in mice." (PMID 24865492, 2014). "Haploinsufficiency of Sox9 in humans leads to the skeletal dysmorphology syndrome campomelic dysplasia underlining the crucial role described for Sox9." (PMID 24976683, 2014). "SOX9 mutations cause campomelic dysplasia (MIM 114290), a skeletal dysplasia characterized by bowed, long bones, small scapula, tracheobronchial narrowing, sex reversal and kyphoscoliosis." (PMID 24023777, 2013). "Heterozygous mutations in Sox9 cause a severe form of chondrodysplasia in humans called camptomelic dysplasia." (PMID 23776632, 2013). "SOX9 mutations can lead to haplo-insufficiency, being responsible for campomelic dysplasia, a skeletal malformation syndrome often associated with XY sex reversal in humans." (PMID 24040047, 2013). "Mutations within and outside of SOX9 leading to haploinsufficiency are known to cause a bone disorder, campomelic dysplasia, in both sexes and gonadal dysgenesis in 75% of XY individuals presenting as females." (PMID 24223201, 2013). "Haploinsufficiency of SOX9 is associated with campomelic dysplasia (CD, OMIM #114290), which is characterized by severe skeletal malformations and sex reversal." (PMID 22719264, 2012).
campomelic dysplasia (continued). "SOX9 function was first identified as a key regulator of cartilage and male gonad development, with mutations in SOX9 causing campomelic dysplasia and autosomal sex reversal." (PMID 22385677, 2012). "Mutations in SOX9 cause campomelic dysplasia characterized by skeletal defects and autosomal sex reversal." (PMID 23284291, 2012). "It has been shown that heterozygous defects in the human Sox9 gene lead to campomelic dysplasia, a skeletal malformation syndrome, which is often linked to XY sex reversal syndrome." (PMID 21991335, 2011). "This is very unusual as rearrangements and mutations affecting SOX9 normally result in patients with campomelic dysplasia (deformity of chondrogenesis) and in some 46,XY cases, gondal dysgenesis." (PMID 21408189, 2011). "Sox9 is a critical transcription factor required for cartilage formation and mutations in Sox9 are associated with campomelic dysplasia, which is characterized by skeletal defects and cranial dismorphology." (PMID 21935430, 2011). "Mutations within and outside of SOX9 are known to cause the bone disorder campomelic dysplasia (CD), which in approximately 70% of cases is associated with 46,XY GD." (PMID 21408189, 2011). "Mutations in human SOX9 cause the skeletal malformation syndrome campomelic dysplasia, which is attributed to the disruption of the chondrogenic differentiation program because of failure to express SOX9 target genes." (PMID 22072985, 2011). "Mutations in SOX9 are associated with the human skeletal malformation syndrome, campomelic dysplasia, in which skeletal abnormalities can be attributed to the disruption of the chondrogenic differentiation program due to failure to express SOX9 target genes." (PMID 22072985, 2011). "Mutations in this domain cause the Sox9-dependent disease “campomelic dysplasia” with skeletal dysmorphology/sex reversal, and this disease is due to loss of transcription activation function." (PMID 21991335, 2011). "Heterozygous mutations in SOX9 cause campomelic dysplasia, a severe skeletal dysmorphology syndrome in humans characterized by a generalized hypoplasia of endochondral bones." (PMID 20404928, 2010). "Heterozygous mutations in Sox9 cause Campomelic Dysplasia (CD), a generalized disease of cartilage characterized by hypoplasia of endochondral bones." (PMID 20404928, 2010). "SOX9 is a transcription factor located at chromosome 17q24, and inactivation of one allele causes campomelic dysplasia (CD)." (PMID 20187927, 2010). "For instance, SOX9 variants may present with isolated RS or with syndromic manifestations such as campomelic dysplasia, leading to very different prognoses." (PMID 41077824, 2026). "Perturbations in these programs, exemplified by mutations in Fgfr3, Sox9, and Dlx5, underlie region-specific skeletal dysplasias, such as achondroplasia, campomelic dysplasia, and split-hand/foot malformation, demonstrating the lasting impacts of embryonic patterning errors." (PMID 41596573, 2026). "Campomelic Dysplasia (CD) is a rare congenital disease caused by haploinsufficiency (HI) in SOX9." (PMID 40025280, 2025). "Furthermore, the mutation of SOX9 can enhance the progression of campomelic syndrome and sex reversal of XY." (PMID 39624466, 2025). "Potentially pathogenic variants were discovered in the FAS and pFAS groups, including those known to cause craniofacial malformations, such as SOX9 (Campomelic Dysplasia), STRA6 (Matthew–Wood), CHD7 (CHARGE), MID1 and MED15 (Opitz–Kaveggia syndrome), and several 22q11.2DS genes." (PMID 38785976, 2024). "SOX9 is critical for AV valve development, including in EndMT and matrix remodelling, and its deregulation or mutation is associated with calcification and campomelic dysplasia, in which valve defects are often present." (PMID 37689753, 2023). "Mutations in SOX9 were identified as the cause of campomelic dysplasia (CD) in humans." (PMID 34112251, 2021).